DNM3 (dynamin 3)
Description:
Microtubule-associated force-producing protein involved in producing microtubule bundles and able to bind and hydrolyze GTP (By similarity). Most probably involved in vesicular trafficking processes, in particular endocytosis (By similarity).
Synonyms: KIAA0820; Dyna III
Tractability: Small molecule: a structure with a bound ligand is known; it has a high-quality binding pocket. Antibody: its Gene Ontology location is reachable by antibodies, with medium confidence. PROTAC: ubiquitination databases record sites on it; its protein half-life has been measured.
Gene: Protein-coding gene on chromosome 1 (171,817,887 to 172,418,466, forward strand). Ensembl gene ENSG00000197959.
Subcellular location: Cytoplasm; Cytoplasm, cytoskeleton
Subcellular location (Human Protein Atlas): Golgi apparatus
Pathways (Reactome):
Immune System: MHC class II antigen presentation; Toll Like Receptor 4 (TLR4) Cascade
Developmental Biology: Recycling pathway of L1
Signal Transduction: Retrograde neurotrophin signalling
Vesicle-mediated transport: Clathrin-mediated endocytosis
Gene Ontology:
Molecular function: protein binding; GTPase activity; microtubule binding; GTP binding
Biological process: endocytosis; filopodium assembly; synapse assembly; synaptic vesicle budding from presynaptic endocytic zone membrane; synaptic vesicle endocytosis
Cellular component: extracellular exosome; dendritic spine; perinuclear region of cytoplasm; plasma membrane; postsynaptic density; synapse; cytoplasm; cytoskeleton; photoreceptor inner segment; presynapse
Genetic constraint (gnomAD): Loss-of-function variants: 40 observed, 75.56 expected, observed/expected ratio (o/e) 0.53, 90% interval 0.41 to 0.69. The upper end of that interval is the gene's LOEUF score, 0.69, which puts it in group 2 of 6, group 1 being the genes least tolerant of losing a copy. Missense variants: 782 observed, 988.37 expected, observed/expected ratio (o/e) 0.79, 90% interval 0.75 to 0.84. Synonymous variants: 365 observed, 351.98 expected, observed/expected ratio (o/e) 1.04, 90% interval 0.95 to 1.13.
Homologues: Orthologues: macaque DNM3 (99% identical), chimpanzee DNM3 (99% identical), pig DNM3 (98% identical), dog DNM3 (98% identical), rabbit DNM3 (98% identical), mouse Dnm3 (98% identical), rat Dnm3 (97% identical), guinea pig DNM3 (92% identical), tropical clawed frog dnm3 (77% identical). Paralogues in human: DNM1 (80% identical), DNM2 (80% identical), DNM1L (35% identical), MX1 (23% identical), MX2 (22% identical), OPA1 (17% identical).